MMP3 (matrix metallopeptidase 3)
Diseases named in the same sentence as MMP3 in open-access papers (continued):
Sharing a sentence is not in itself a finding about the gene and the disease.
Cerebral ischemia (10 papers, 2013 to 2025). Restriction of arterial blood supply to the brain associated with insufficient oxygenation to support the metabolic requirements of the tissue. "The focus of the present study was to determine the time-dependent effects of the duration of ischemia and r-tPA treatment on brain injury, neurobehavioral outcomes, and the expression of MMPs (MMP-9, MMP-2, and MMP-3) in cerebral ischemia with reperfusion." (PMID 39273389, 2024). "After cerebral ischemia/reperfusion, MMP‐3 was activated and observed in neurons, endothelial cells, and macrophages and participated in the pathogenesis of stroke." (PMID 38379112, 2024). "Three in MMP family members, MMP2, MMP9 (referred to as the gelatinases), and MMP3, are thought to be activated within the ischemic lesion where they are critical to injury progression during and after cerebral ischemia." (PMID 30723388, 2019). "RNA-seq revealed significant MMP-3 up-regulation (highly expressed up to 21 days after cerebral ischemia)." (PMID 29896414, 2018). "For MMP-3 and TIMP-3 a trend for the association with cerebral ischemia was observed (p = 0,06 and p = 0.054)." (PMID 23555845, 2013). "Furthermore, in the cerebral ischemia‐reperfusion model, neuroinflammation mediated by MMP‐3 and MMP9 is important for white matter damage and oligodendrocyte apoptosis." (PMID 40864831, 2025). "Besides MMP‐2, MMP‐3, and MMP‐9, other MMPs such as MMP‐1, MMP‐7, MMP‐8, and MMP‐12 have also been implicated in cerebral ischemia–reperfusion injury, although their specific roles and mechanisms are still being investigated." (PMID 38379112, 2024). "We find that tPA treatment further decreases MMP-3 levels following cerebral ischemia, which may explain the bigger infarct volume and worsen neurologic dysfunction in tPA group." (PMID 39273389, 2024). "However, MMP-3 expression by activated astrocytes is suppressed following cerebral ischemia, and the downregulation of MMP-3 contributes to the suppression of BBB breakdown." (PMID 36675113, 2023). "In addition, MMP-3 can activate MMP-9 following cerebral ischemia." (PMID 39273389, 2024). "One study did show a significant rise in MMP3 protein levels 24 h after the induction of cerebral ischemia, and however, the study involved a photochemically-induced permanent ischemia model, which may be responsible for the differences in MMP3 expression compared to the present study." (PMID 30723388, 2019). "After knocking out the tissue inhibitor of metalloproteinases‐3 (TIMP‐3) in mice, it can reduce the expression of MMP3 and MMP9 and reduce the death of immature oligodendrocytes after cerebral ischemia." (PMID 40864831, 2025). "In conclusion, our findings demonstrated that M2 microglial EVs attenuated BBB disruption after cerebral ischemia by delivering miR-23a-5p, which targeted TNF and regulated MMP3 and NFκB p65 expression." (PMID 37611902, 2024). "The mechanistic study revealed that M2 microglial EVs attenuated BBB disruption in the acute stage of cerebral ischemia by delivering miR-23a-5p, which targeted TNF and regulated MMP3 and NFκB p65 expression." (PMID 37611902, 2024).
oral cancer (10 papers, 2010 to 2025). "Chunwen Su showed that MMP3 could be used as a potential biomarker of oral cancer progression." (PMID 36941602, 2023). "After analyzing the data related to oral cancer using the Cancer Genome Atlas, Oncomine, and Kaplan-Meier mapper, the MMP3 and MMP10 are identified as highly altered hub genes of oral cancer." (PMID 38302910, 2024). "In contrast, in the KB oral cancer cells that were treated with berberine, the expression of MMP-2 and MMP-3 was regulated by the p38 MAPK signaling pathway." (PMID 25634589, 2015). "Hence, it suggests that SMAD3, MMP3, SERPINE1, and THBS1 serve as tumor promoters in oral cancer." (PMID 36033831, 2022).
preeclampsia (10 papers, 2017 to 2025). Preeclampsia is a hypertensive disorder of pregnancy that is characterized by new-onset hypertension with proteinuria presenting after 20 weeks of gestation, and depending on mild or severe forms may initially present with severe headache, visual disturbances, and hyperreflexia. "While MMP-2 and MMP-9 are physiologically involved in trophoblast invasion and angiogenesis, and MMP-3 in cervical remodeling, their overexpression has been associated with pregnancy complications such as preeclampsia, infection, and preterm labor." (PMID 41450943, 2025). "The occurrence of 1G/1G MMP1 or 5A/5A MMP3 genotype in the mother or 1G/1G MMP1 or 5A/6A MMP3 genotype in the child is associated with preeclampsia development." (PMID 29670668, 2018). "To summarize, our findings suggest that maternal SNPs −1607 1G/1G MMP1 and −1171 5A/5A MMP3 are independency important genetic factors associated with the occurrence of preeclampsia in Polish population." (PMID 29670668, 2018). "The fetal set of 1G/1G MMP1- and 5A/6A MMP3-studied polymorphisms also contributes to maternal predisposition of occurrence of preeclampsia OR = 6.54 (95% CI 2.13–20.01, p < 0.01)." (PMID 29670668, 2018). "The simultaneous carriage of 1G/1G MMP1 and 5A/5A MMP3 polymorphisms by mother increases over 10-fold her risk to preeclampsia development." (PMID 29670668, 2018). "When both mother and fetus are carriers of both 5A/5A and 5A/6A MMP3 polymorphisms, respectively, the risk of occurrence of preeclampsia is doubled OR = 4.57 (95% CI 1.85–11.26)." (PMID 29670668, 2018). "These analyses revealed that simultaneously maternal homozygosity in 1G/1G MMP1 and 5A/5A MMP3 increases the risk of preeclampsia development over 10-fold (OR = 10.22, 95% CI 2.28–45.8; p < 0.01)." (PMID 29670668, 2018). "Interestingly, elevated plasma levels of another member of the MMP family, MMP3, is a risk factor for cardiovascular disease, and elevated levels of this protein are also associated to early-onset preeclampsia at time of diagnosis." (PMID 38253981, 2024). "Interestingly, the majority of children born from mothers who developed preeclampsia were heterozygous 5A/6A: a genotype associated with moderate MMP3 level." (PMID 29670668, 2018). "Our findings also associate carriage of MMP3 5A/6A with the appearance of preeclampsia." (PMID 29670668, 2018). "Moreover, simultaneous maternal and fetal 1G/1G homozygosity increases the risk of preeclampsia development 2.39-fold and the set of maternal 5A/5A and fetal 5A/6A MMP3 genotypes by over 4.5 times." (PMID 29670668, 2018). "It is also feasible that higher maternal levels of MMP-3 in early-onset preeclampsia may cause the disease or ability of compensation for occurring disturbances." (PMID 28798935, 2017). "Additionally, simultaneous maternal and fetal 1G/1G homozygosity increases the risk of preeclampsia development 2.39-fold, whereas the set of maternal 5A/5A and fetal 5A/6A MMP3 genotypes elevated the risk of occurrence of the studied disease by over 4.5 times." (PMID 29670668, 2018). "We also observed that the fetal genotype elevates the maternal risk of preeclampsia development (OR = 6.54, 95% CI 2.13–20.01; p < 0.01) for simultaneous carriers of 1G/1G MMP1 and 5A/6A MMP3 polymorphisms." (PMID 29670668, 2018). "One new and important finding of the present study was that MMP-3 levels were significantly higher in the earlyPre group than in the preeclamptic patients with late-onset preeclampsia (latePre group) and the controls." (PMID 28798935, 2017). "MMP-3 levels were significantly higher in the patients with early-onset preeclampsia than in the late-onset preeclampsia and the controls." (PMID 28798935, 2017). "One important finding of the present study was that MMP-3 levels were significantly higher in the earlyPre group than in the preeclamptic patients with late-onset preeclampsia (latePre group) and the controls." (PMID 28798935, 2017).
preeclampsia (continued). "Levels of MMP-3 were significantly higher in preeclamptic patients with early-onset disease; however, the MMP-3 levels in patients with late-onset preeclampsia were similar to those observed in the control subjects." (PMID 28798935, 2017). "Importantly, a reduction in MMP3 expression in EVTs surrounding spiral arteries was reported in patients with severe preeclampsia as compared to healthy controls." (PMID 41450565, 2025). "The aim of the present study was to determine whether the most common MMP1, MMP2, MMP3, and MMP9 gene polymorphisms in maternal and fetal genes are associated with preeclampsia." (PMID 29670668, 2018). "The present study examines whether the occurrence of single-nucleotide polymorphisms (SNP) in the MMP1, MMP2, MMP3, and MMP9 genes is related to the outcome of preeclampsia." (PMID 29670668, 2018). "This may explain various observations according to MMP3 levels and preeclampsia presented in numerous studies." (PMID 29670668, 2018). "The maternal 1G/1G MMP1 and 5A/5A MMP3 and fetal 1G/1G MMP1 and 5A/6A MMP3 gene polymorphisms may be strong genetic markers of preeclampsia, occurring either individually or together." (PMID 29670668, 2018). "In contrast reduced MMP-3 expression in the extravillous trophoblast around spiral arteries was observed in pregnancies complicated by severe preeclampsia and in patients with pregnancies complicated by early-onset preeclampsia with IUGR." (PMID 28798935, 2017). "GDS3467 and GDS2080 studies included in the GEO Profile database demonstrate a lack of association between placental MMP3 gene expression levels and preeclampsia, whereas others show downregulation of MMP3 levels in preeclamptic fetal origin cells and in preeclamptic extravillous trophoblast cells." (PMID 29670668, 2018). "Moreover, this analysis pointed out that the carriage of 5A/6A genotype by male children is associated to preeclampsia occurrence whereas male fetal homozygous 6A/6A of MMP3 dominate in noncomplicated pregnancies." (PMID 29670668, 2018). "Furthermore, MMP-3 appears to be involved solely in early-onset preeclampsia." (PMID 28798935, 2017). "MMP-3 levels were significantly higher in patients with early-onset preeclampsia; though the MMP-3 levels in patients with late-onset preeclampsia were similar to those observed in healthy controls." (PMID 33803206, 2021). "In addition, these genes were elevated in the placentas of preeclampsia patients, including LRP1, COL6A1, ITGB2, and MMP3." (PMID 38003549, 2023). "One important finding of the present study was that MMP-3 appears to be involved solely in early-onset preeclampsia, but not in late-onset preeclampsia." (PMID 28798935, 2017).
type 2 diabetes (10 papers, 2007 to 2025). "In accordance with our study, in type 2 diabetic patients, high interstitial MMP-3 mRNA expression was associated with higher degrees of interstitial injury." (PMID 25848912, 2015). "In our previous study using a genetic model of type 2 diabetes (the db/db mouse), we assessed potential effects on genes linked to cardiotoxicity genes (Kcnk1, Asah2, B4glant, MMP-3), and reported no adverse effects after ENOblock treatment." (PMID 30679508, 2019). "Super-induction of MMP-3 by pioglitazone may have important implications for patients using pioglitazone to treat type II diabetes in the presence of chronic inflammation." (PMID 17319946, 2007). "Consequently, the expression of MMP-3 and MMP-14 may be valuable as markers for periodontal inflammation in individuals with type 2 diabetes." (PMID 40075856, 2025).
viral infection (10 papers, 2014 to 2025). "Such a technique is notoriously resistant to pre-analytical variables, so a genuine biological association of functional genetic variant of MMP3 with virus infection can be bona fide demonstrated." (PMID 35204780, 2022). "It has been reported that MMP-3 exhibits broad-spectrum antiviral activities, enhancing host antiviral immunity to restrict viral infections." (PMID 39723192, 2024). "In line with our study, other studies about virus infection and MMP3 expression display similar results." (PMID 32922541, 2020). "The E1A mutant infection resulted in more MMP3 mRNA in infected mouse brains than did the wt virus infection, and the difference was statistically significant." (PMID 27303733, 2016). "This study suggested a novel role of MMP3 in nucleus during viral infection and provided new evidence for MMPs in immunomodulation." (PMID 24416274, 2014). "In our present study, we indicated that MMP3 was translocated into the cell nucleus upon virus infection." (PMID 24416274, 2014). "And here we showed that during virus infection, MMP3 protein level was evaluated, and MMP3 was translocated into cell nucleus and interacted with and further activated NFκB." (PMID 24416274, 2014). "Viral infections may activate the expression of MMP3 in astrocytes and MMP12 in CNS cells and infiltrating cells." (PMID 38803919, 2024). "MMP-3 expression increases during the activation of EBV viral infection." (PMID 36362386, 2022). "But to date, the role of MMP3 during virus infection remains largely unknown." (PMID 24416274, 2014). "However, the role of MMP3 during virus infection is unclear." (PMID 24416274, 2014). "This correlation suggests that in the disease state, both MMP-3 and TIMP-1 are upregulated in tandem, possibly reflecting a coordinated response to viral infection and inflammation in ARN." (PMID 39723192, 2024). "In the brain, activity of MMP2, MMP3, and MMP9 is induced under pathological conditions, including viral infection." (PMID 27303733, 2016). "It is not clear, thus far, whether MMP-3 expression during virus infection improves its virulence, assists in the development of a chronic disease, or represents a defensive mechanism of the host." (PMID 35204780, 2022).
head and neck cancer (9 papers, 2009 to 2024). A primary or metastatic malignant neoplasm affecting the head and neck. "Through HPA database, we also found that PTGS2 and MMP3 are expressed in various cancers, including head and neck cancers." (PMID 36555343, 2022). "A study of patient-derived tumor samples in the Cancer Genome Atlas database showed that CCN2 expression was higher in head and neck cancers, and high expression of CCN2 and MMP3 was associated with worse prognosis in head and neck cancers." (PMID 35042954, 2022). "Many carcinomas express stromelysins; for example, MMP-3 and -10 produced by the head and neck carcinomas are higher than in normal-matched tissue." (PMID 20649989, 2010). "Likewise, MMP-3 has been associated with vascular invasion in EC and AXL has been reported to induce MMP-3 expression in head and neck cancer cell invasion." (PMID 27764792, 2016). "Among the SASP factors we investigated in the current study, in addition to MMP1 and MMP3, overexpression of MMP10 has been reported to promote invasion, metastasis in head and neck cancer, and tongue cancer." (PMID 39756915, 2024).
keloid (9 papers, 2012 to 2024). An irregularly shaped, elevated mark on the skin caused by deposits of excessive amounts of collagen during wound healing. "The baseline keloid model comprising the entire keloid showed no increase in epidermal thickness, but reduced COL4A2, HAS1 and MMP3 gene expression in the dermal compartment of the keloid model compared to the normal skin model." (PMID 30370495, 2018). "The majority of literatures reported the upregulation of MMP1 and MMP3, because they greatly contributed to the invasion of KFs, allowing the keloids to extend beyond the wound boundary." (PMID 27339758, 2016). "Increasing expression of decorin by adenovirus in keloid fibroblasts significantly decreased collagen synthesis and stimulated the transcription level of MMP-1 and MMP-3." (PMID 34768882, 2021). "The results demonstrated that keloid dermal fibroblasts exhibited significantly increased expression of MMP-1, MMP-2, and MMP-3 relative to normal or hypertrophic dermal fibroblasts." (PMID 33672186, 2021). "However, in keloid fibroblasts, MMP-1, which cleaves collagen types I and III, is decreased, while MMP-3, a stromelysin, is increased." (PMID 38892032, 2024). "To further explore the impact of EP on the expression of ECM-degrading enzymes in keloids, we assessed the mRNA expression levels of metalloproteinase I (MMP1), metalloproteinase III (MMP3), and tissue inhibitor of metalloproteinases I (TIMP1) in both TGF-β1-treated HDFs and KFs." (PMID 38892032, 2024). "MMP1 and MMP3 were expressed at lower levels in keloid ESS compared with normal ESS and were not significantly increased after wounding." (PMID 22536458, 2012).
metastatic tumors (9 papers, 2005 to 2022). "A selective inhibitor of MMP3 is available (UK370106) but is yet to be tested for inhibition of primary tumor or metastatic tumor growth." (PMID 32854182, 2020). "High levels of MMP-3, MMP-9 and VEGF have all been associated with metastasis in NPC and can therefore serve as endpoint measurement for metastatic disease." (PMID 20964870, 2010). "The differential expression of MMP3 in primary and metastatic tumours of patient 1 and 7 and of MMP9 in patient 1 and 15 could be confirmed by quantitative real-time PCR." (PMID 16189523, 2005). "In HNSCC patients, significantly higher MMP-3, MMP-9 and vimentin levels were found in metastatic tumors." (PMID 28489600, 2017). "In patients with metastasis the estimated expression of MMP-3 and uPA (resp., 28% and 45%) was higher than that from no metastatic tumors; it means there is higher expression of both markers in metastatic tumors (p < 0.05)." (PMID 27975070, 2016). "We concluded that overexpression of MMP-3 and uPA, altogether with diminished expression of PAI-1 from metastatic tumors, might be a crucial step towards metastasis in ductal breast cancer." (PMID 27975070, 2016). "Despite the increasing evidence regarding MMP3, neither the selective inhibitor of MMP3 (UK370106) or the generic MMP inhibitor (marimastat) have been assessed in relation to restricting primary tumors or metastatic tumor growth in canine or human OSA, despite some trials in other tumor types." (PMID 36570509, 2022). "MMP3 in canine OSA could be used as marker of more invasive and metastatic tumors." (PMID 34414229, 2021). "Evaluation of expression of MMP-1, MMP-3, MMP-9, and TIMP-1 in 54 samples from patients with no metastatic tumors in lymph nodes was indirectly estimated by obtaining numeric values of intensity IOD, from the corresponding immunohistochemistry results (standard process)." (PMID 27975070, 2016).